CFD (complement factor D)
Diseases named in the same sentence as CFD in open-access papers (continued):
Sharing a sentence is not in itself a finding about the gene and the disease.
meningococcal infection (2 papers, 2021 to 2025). Infections with bacteria of the species neisseria meningitidis. "Especially in humans, deficiency in factors of the alternative complement pathway such as CFD or properdin is reported to be associated with meningococcal infection and fulminant septic shock." (PMID 34396466, 2021).
papillary thyroid cancer (2 papers, 2020 to 2024). "The hub gene CFD was identified and validated as a potential target gene in papillary thyroid cancer." (PMID 32117620, 2020). "Furthermore, in papillary thyroid carcinoma, a group of iCAFs with a remarkable expression of CFD, DCN, or CCDC80, facilitated the migration of tumor cells through ECM degradation." (PMID 39003267, 2024).
paroxysmal nocturnal hemoglobinuria (2 papers, 2024 to 2025). Paroxysmal nocturnal hemoglobinuria (PNH) is an acquired clonal hematopoietic stem cell disorder characterized by corpuscular hemolytic anemia, bone marrow failure and frequent thrombotic events. "Danicopan (VoydeyaTM) is a complement factor D inhibitor indicated to treat extravascular hemolysis with paroxysmal nocturnal hemoglobinuria." (PMID 39942587, 2025). "Danicopan is an oral small molecule complement factor D (FD) inhibitor that showed improved benefit-risk profile as add-on therapy to ravulizumab or eculizumab in patients with complement-mediated paroxysmal nocturnal hemoglobinuria (PNH) compared to placebo." (PMID 38903526, 2024).
uremia (2 papers, 2018 to 2024). A clinical syndrome associated with the retention of renal waste products or uremic toxins in the blood. "Complement factor D as one of the elements of the complement cascade is retained in uremia and has since long been considered to be one of the factors contributing to the pro-inflammatory status of uremia." (PMID 29316724, 2018).
viral infection (2 papers, 2014 to 2022). "CTB 2 cells highly expressed CLU, CFD, and IFIT3, suggesting roles in responding to bacterial or viral infection through the innate arm of the immune system." (PMID 35796428, 2022).
acute kidney injury (1 paper, 2025). Sudden and sustained deterioration of the kidney function characterized by decreased glomerular filtration rate, increased serum creatinine or oliguria. "Acute kidney injury, on the other hand, lead to the accumulation and elevated levels of low-molecular-weight plasma proteins, such as Complement factor D (CFD)." (PMID 40875167, 2025).
age-related macular degeneration (1 paper, 2019). Age-related loss of vision in the central portion of the retina (macula), secondary to retinal degeneration. "Moreover, complement factor D (CFD) and complement factor H (CFH) are important regulators of the complement system and are associated with diseases, such as age-related macular degeneration." (PMID 31861421, 2019).
atrial fibrillation (1 paper, 2024). A disorder characterized by an electrocardiographic finding of a supraventricular arrhythmia characterized by the replacement of consistent P waves by rapid oscillations or fibrillatory waves that vary in size, shape and timing and are accompanied by an irregular ventricular response. "Gene expression analysis revealed that the CFD gene was highly abundant in the EAT of patients with atrial fibrillation (AF)." (PMID 39416783, 2024).
atypical hemolytic-uremic syndrome (1 paper, 2022). A rare, genetic thrombotic microangiopathy due to dysregulation of the alternative complement pathway and characterized by the triad of hemolytic anemia, thrombocytopenia, and acute renal dysfunction. "In addition, CFB cleavage is abrogated in aHUS (atypical hemolytic uremic syndrome) patients’ serum when using danicopan, which is an oral CFD inhibitor." (PMID 36582241, 2022).
autoimmune disease (1 paper, 2024). A disorder resulting from loss of function or tissue destruction of an organ or multiple organs, arising from humoral or cellular immune responses of the individual to their own tissue constituents. "Adipsin is a vital adipokine and one of the components of complement factor D, participating in the pathogenesis of various autoimmune diseases." (PMID 38817600, 2024).
C3 glomerulopathy (1 paper, 2024). "Several small-molecule CFD inhibitors have entered clinical trials for treating diseases mediated by the AP, such as C3 glomerulopathy, and aHUS19." (PMID 39009768, 2024).
chondrosarcoma (1 paper, 2024). A malignant cartilaginous matrix-producing mesenchymal neoplasm arising from the bone and soft tissue. "Here, we observed a gCAF subcluster (CD68, HLA-DPB1, and CFD) in conventional central chondrosarcoma, which was characterised by granulocyte activation." (PMID 38267611, 2024).
diabetic cardiomyopathy (1 paper, 2024). Diabetic cardiomyopathy is a disorder of the heart muscle in people with diabetes. "Overexpression of CFD relieves cardiac remodeling and improves cardiac function both in mice and rats with diabetic cardiomyopathy." (PMID 39416783, 2024).
diabetic nephropathy (1 paper, 2021). "Our results show that expression levels of CFD in rat urine, kidney tissue, and clinical samples were increased by progression of diabetic nephropathy." (PMID 33922243, 2021). "However, this study is the first to demonstrate that expression levels of CFD in rat urine, as well as patients’ urine, can be used in diagnosis of diabetic nephropathy." (PMID 33922243, 2021). "The reliability of C4b, CFD, CXCR6, and LIF as a biomarker for detecting diabetic nephropathy was investigated in clinical trials." (PMID 33922243, 2021). "Using diabetic nephropathy models, data demonstrate that urinary levels of C4b, CXCR6, CFD, and LIF were markedly increased compared with conventional biomarkers (KIM-1, NGAL)." (PMID 33922243, 2021). "The urinary levels of C4b, CFD, CXCR6, LIF, KIM-1, and NGAL were markedly increased in diabetic nephropathy patients compared to normal subjects." (PMID 33922243, 2021). "Based on a preliminary scale of clinical urine tests, it was also found that C4b, CXCR6, CFD, and LIF were demonstrated to be biomarker candidates for early detection of diabetic nephropathy." (PMID 33922243, 2021). "Further, urinary C4b, CXCR6, CFD, and LIF levels might also potentially be employed as biomarkers to monitor the effectiveness of pharmacological interventions in diabetic nephropathy patients." (PMID 33922243, 2021). "Thus, we selected the complementary complement 4b (C4b), complement factor D (CFD), C-X-C motif Chemokine Receptor 6 (CXCR6), and leukemia inhibitory factor (LIF) as candidate biomarkers for early detection of diabetic nephropathy." (PMID 33922243, 2021). "CFD does not seem to be involved in pathogenesis of diabetic nephropathy." (PMID 33922243, 2021).
disc degeneration (1 paper, 2022). "However, within these processes, only a few genes were commonly upregulated in human cluster D2 and N153S tissues, including BIRC3, CFD, RSAD2, and ALCAM – none of which are considered inflammatory hallmarks of disc degeneration." (PMID 35769461, 2022).
endometritis (1 paper, 2020). An acute or chronic, usually bacterial infectious process affecting the endometrium. "The results revealed the dysregulation of the six crucial biomarkers involved in endometritis: SLC7A5, COL1A1, AXIN2 (upregulated); CFD, MGP, CCDC3 (downregulated)." (PMID 32545766, 2020). "This study confirmed differences in the expression profiles of six biomarkers in LPS-induced bovine endometritis: SLC7A5, COL1A1, AXIN2 (upregulated) and CFD, MGP, CCDC3 (downregulated)." (PMID 32545766, 2020).
Hepatic fibrosis (1 paper, 2021). The presence of excessive fibrous connective tissue in the liver. "Therefore, the expression of CFD in the serum samples from SHF-F2 and SHF-F4 patients may be a potential biomarker for distinguishing the stage of advanced S. japonicum-induced hepatic fibrosis." (PMID 33933138, 2021).
hyperopia (1 paper, 2017). A refractive error in which rays of light entering the eye parallel to the optic axis are brought to a focus behind the retina, as a result of the eyeball being too short from front to back. "A diverse range of complement-related genes were differentially-expressed, with components and regulators of both the classical and alternate pathways up-regulated in late myopia (CS1, PROS1, C1QB and CFD) and late hyperopia (SERPING1, C1QA, CRP, C7 and CFD)." (PMID 28852117, 2017).
leukopenia (1 paper, 2016). "Uraemic retention solutes such as parathyroid hormone, polyamines, angiongenin and complement factor D may all impair neutrophil activity by causing inappropriate expression of cell adhesion molecules that result in a transient leukopenia." (PMID 27090094, 2016).
migraine (1 paper, 2023). "Remaining genes differentially methylated in migraine were kinesin family member 26A (KIF26A), dedicator of cytokinesis 6 (DOCK6), and complement factor D (CFD) that were reported to associate with various aspects of the aging process." (PMID 37199585, 2023).
neuropathy (1 paper, 2021). A disorder affecting the nervous system that manifests with pain, tingling, numbness, and/or muscle weakness. "In our study, we were the first to demonstrate an increase in the expression of genes regulating the complement system such as CFP encoding properdin and CFD encoding Factor D in patients with neuropathy." (PMID 34640602, 2021).
open spina bifida (1 paper, 2025). "The CPA/HA, CPL/OFD, and CFD/OFD ratios were all significantly higher in fetuses with open spina bifida (OSB) (p < 0.05)." (PMID 41267861, 2025).
ovarian carcinoma (1 paper, 2025). A malignant neoplasm originating from the surface ovarian epithelium. "For instance, in BRCA1-mut ovarian cancer, KTR14, KRT16, CXCL9, and CFD were highly upregulated (more than 4-fold change), and in BRCA2-mut ovarian cancers, TSPAN7 and CDKN2C were clearly upregulated (more than 2-fold change)." (PMID 40647506, 2025).
periodontitis (1 paper, 2025). An acute or chronic inflammatory process that affects the tissues that surround and support the teeth. "Previous studies have reported heterogeneity in gingival fibroblasts in periodontal tissues, with four subsets significantly altered in periodontitis: Fib 1.1 (CXCL1, CXCL2, CXCL13); Fib 1.2 (APCDD1, IGFBP2, MRPS6); Fib 1.3 (APOD, GSN, CFD); and Fib 1.4 (TIMP3, ASPN, COL11A1)." (PMID 40801798, 2025).
prostate carcinoma (1 paper, 2021). A carcinoma that arises from epithelial cells of the prostate gland. "Apart from cellular mechanism, recent studies reported that the disruption of TGFβR3 induced the dysregulation of the complement components, including C4a and the complement factor D in breast and prostate cancer." (PMID 33805946, 2021).
prostate tumours (1 paper, 2020). "Reduced C7 mRNA (p = 0.0244) and CFD and C7 protein expression was validated in murine prostate tumours." (PMID 31740786, 2020).
retinal degeneration (1 paper, 2023). Degeneration of the retina. "The real-time RT-PCR was conducted to examine the expression of complement genes (C1q, C2, C3, C4, CFI and CFD) in the guinea pig model of long-term form deprivation-induced myopic retinal degeneration." (PMID 37448698, 2023).
schistosomiasis (1 paper, 2021). An infectious disease caused by parasitic trematodes of the genus Schistosoma that colonize human blood vessels and release eggs that can cause granulomatous reactions leading to acute (swimmer's itch or acute schistosomiasis syndrome) or chronic disease. "Based on the hierarchal clustering analysis results and key modulated signalling pathways, the proteins complement C1q subcomponent subunit A (C1QA, 1.82-fold) and complement factor D (CFD, 2.51-fold) were differentially expressed in the SHF-F4 and SHF-F2 groups of schistosomiasis patients." (PMID 33933138, 2021).
staphylococcus aureus infection (1 paper, 2018). An infectious process in which the bacteria Staphylococcus aureus is present. "Among which, we also performed the PPI network of several DEGS including C3, HLA-DRB5, ICAM1 and HLA-DRB1, ITGAM, and CFD that involved in the staphylococcus aureus infection signaling pathway." (PMID 30186855, 2018).
steatosis (1 paper, 2009). Increased lipid within the cytoplasm of cells. "The genes we identified as steatosis-associated by the network analysis, such as ACOX1, SCD, PPARγ, CFD and CIDEC were re-discovered by the regression analysis." (PMID 19680557, 2009).
thrombotic microangiopathy (1 paper, 2025). The syndromes of microangiopathic hemolytic anemia, thrombocytopenia, and variable signs of organ impairment, due to platelet aggregation in the microcirculation. "Patients with LN with thrombotic microangiopathy have stronger staining intensity and deposition of MBL, MASP1/3, CFB, CFD, C4d, and VWF." (PMID 41031884, 2025).
thymoma (1 paper, 2020). A neoplasm arising from the epithelial cells of the thymus. "Further comparison of protein expression profiles between thymoma and TSCC identified several extracellular matrix (ECM) proteins, such as CFD, TIMP1, and VCAN, that are overexpressed in TSCC and involved in complement activation and inflammation process." (PMID 31967407, 2020).
tumor (29 papers, 2010 to 2026). "Our findings demonstrated a substantial downregulation of CFD in tumour patients, wherein its effector activity predominantly suppresses pathways that promoted tumourigenesis." (PMID 40429821, 2025). "Upon analyzing the expression of 11 model genes in prostate PRAD, we observed significant differential expression of eight genes (MYADM, MPDZ, LTBP2, DENND4C, PROK1, DDIT4, IGFBP3, and CFD) between normal and tumor tissues." (PMID 38898043, 2024). "Next, we analyzed the expression of CFD in AML patients using the UALCAN database and found that the expression of CFD was highest in AML patients in comparison with other tumor patients." (PMID 39310420, 2024). "The expression level of ALDH1A1 and CFD was significantly higher in the tumor group compared with the normal group." (PMID 37359050, 2023). "We also selected the CFD gene, which singularly exhibited a methylated area in each tumor cell line." (PMID 34454589, 2021). "Given that CAFs are reported to be an important stromal component and are critically involved in tumor progression, we reclustered the CAFs and further categorized them into two main types: inflammatory CAFs (iCAFs; CFD, CKB, and DPT) and myoblastic CAFs (myCAFs; INHBA, SULF1, and COL8A1)." (PMID 36725337, 2023). "Subgroup 3 and 7 expressed inflammatory subtypes such as CFD, PDGFRA and DCN, and the remaining tumour cells expressing inflammatory markers were named iCAF." (PMID 39789383, 2025). "In contrast, ADAMDEC1+ Fibro, C3+ Fibro, CFD+ Fibro, DPT+ Fibro, Proliferating Fibro, and Myo Fibro were present in both tumor and normal tissues and were therefore classified under the Fibro group." (PMID 41031085, 2025). "For example, C03_PI16 expressed several marker genes, such as COL14A1, CFD, GSN and PI16, similar to the major fibroblast subpopulations in normal tissue and early‐stage tumour in a previous study." (PMID 38115703, 2023). "Adipsin, known as complement factor D, can maintain AT homeostasis, and is primarily expressed in monocytes, macrophages AT, and ADSC within tumor tissue." (PMID 35701840, 2022). "Compared to fibroblasts from normal tissues, the top upregulated genes in tumor-derived fibroblasts were CXCL8, CXCL2, CCL2, CXCL3 and CXCL1, and the top downregulated genes were IGFBP5, PTGDS, CCN5, CFD, and RAMP1." (PMID 36357663, 2022). "Differential expression of seven of these genes (CFD, ALDH18A1, CHKA, DDIT3, ITGA6, PSPH and SQLE) was replicated in another set of 12 paired NASH-HCCs and adjacent non-tumor livers by RT-qPCR (all P < 0.05 by paired t test)." (PMID 30367044, 2018). "Both CFD and CDH7 expression levels were observed to be downregulated in the tumour group." (PMID 40429821, 2025). "We found that CAF subtypes 0 (BTG1+ CAF), 2 (CFD+ CAF), and 4 (IGFBP7+ CAF) were more abundant in the tumor than the normal, while CAF subcluster 1 (OGN+ CAF), 3 (C1R+ CAF), 5 (MFAP5+ CAF), and 6 (SFRP4+ CAF) were more abundant in the normal than the tumor." (PMID 38686196, 2024). "We have defined the top 5 marker genes (ADH1B, CFD (DF), SEPP1 (SELENOP), DCN, and A2M) that could be used for the identification of ADH1B+ CAFs in tumor tissues." (PMID 37848457, 2023). "Similarly, 3 markers (CFD, LEP and DKK3) were downregulated both in tumour lysates and plasma from patients with cancer." (PMID 34997107, 2022). "CFD/Adipsin median levels were found to be lower in tumours compared to the levels in PN and AN (p = 0.0324), while CXCL5/ENA78, CCL20/MIP-3α, IGFBP3, SPP1/OPN and TIMP1 were increased in PN and tumours relative to AN, with higher levels seen in tumours." (PMID 21092330, 2010). "The elevated expression of CFD in AML cells, as compared to other tumor cell lines and normal groups, underscores its potential as a specific biomarker for AML." (PMID 39310420, 2024).
cancer (15 papers, 2018 to 2026). A tumor composed of atypical neoplastic, often pleomorphic cells that invade other tissues. "The PPI networks and survival analysis identified two important genes, ALDH1A1 and CFD, that are strongly associated with the progression of tumors and cancer." (PMID 37359050, 2023). "Specifically, CFD has been identified as a rate-limiting enzyme that plays a crucial role in the activation of the alternative complement pathway and innate immune response across multiple cancer types." (PMID 40429821, 2025). "Specifically, genes such as CFD and MYADM primarily function as prognostic biomarkers, playing a crucial role in predicting the prognosis and clinical outcomes of cancer patients." (PMID 40429821, 2025). "As for TGFBI, CFD, and MGP, MM patients displayed the highest median plasma concentration in comparison to the other cancer patients." (PMID 37835457, 2023). "We demonstrated for the first time the aberrant expression of cancer-related genes (ALCAM, ITGA6, DDIT3, MAP3K6 and PAK1) and metabolism-related genes (ALDH18A1, CAD, CHKA, POLD4, PSPH, SQLE and CFD) in human NASH-HCCs." (PMID 30367044, 2018). "Complement factor D (CFD) was a rate-limiting enzyme, implicating in the alternative complement pathway activation and involving in an innate immune pathway in numerous cancers." (PMID 34053447, 2021).